HOXB2 (homeobox B2)
Description:
Sequence-specific transcription factor which is part of a developmental regulatory system that provides cells with specific positional identities on the anterior-posterior axis.
Synonyms: HOX2H; HOX2; Hox-2.8; K8
Tractability: No criterion of Open Targets' tractability assessment is met for any kind of drug.
Gene: Protein-coding gene on chromosome 17 (48,540,894 to 48,545,109, reverse strand). Ensembl gene ENSG00000173917.
Subcellular location: Nucleus
Subcellular location (Human Protein Atlas): Nucleoplasm
Pathways (Reactome):
Developmental Biology: Activation of anterior HOX genes in hindbrain development during early embryogenesis
Gene Ontology:
Molecular function: DNA-binding transcription activator activity, RNA polymerase II-specific; protein binding; sequence-specific DNA binding; sequence-specific double-stranded DNA binding; DNA-binding transcription factor activity, RNA polymerase II-specific; RNA polymerase II cis-regulatory region sequence-specific DNA binding; DNA binding; DNA-binding transcription factor activity
Biological process: positive regulation of transcription by RNA polymerase II; nervous system development; regulation of transcription by RNA polymerase II; regulation of DNA-templated transcription
Cellular component: nucleoplasm; chromatin; nucleus
Genetic constraint (gnomAD): Loss-of-function variants: 14 observed, 13.09 expected, observed/expected ratio (o/e) 1.07, 90% interval 0.7 to 1.65. The upper end of that interval is the gene's LOEUF score, 1.65, which puts it in group 6 of 6, group 1 being the genes least tolerant of losing a copy. Missense variants: 576 observed, 487.6 expected, observed/expected ratio (o/e) 1.18, 90% interval 1.1 to 1.27. Synonymous variants: 261 observed, 237.19 expected, observed/expected ratio (o/e) 1.1, 90% interval 0.99 to 1.22.
Homologues: Orthologues: chimpanzee HOXB2 (99% identical), macaque HOXB2 (96% identical), pig HOXB2 (87% identical), dog HOXB2 (86% identical), rabbit HOXB2 (84% identical), rat Hoxb2 (81% identical), mouse Hoxb2 (80% identical), guinea pig HOXB2 (80% identical), zebrafish hoxb2a (60% identical), tropical clawed frog hoxb2 (56% identical), Drosophila melanogaster pb (32% identical). Paralogues in human: HOXA2 (50% identical), HOXA3 (27% identical), HOXB3 (26% identical), HOXD3 (26% identical), PDX1 (22% identical), HOXA1 (20% identical), HOXA4 (19% identical), HOXB1 (19% identical), HOXB4 (19% identical), HOXD4 (19% identical), TLX3 (19% identical), HOXC4 (18% identical), and 30 more.
Diseases named in the same sentence as HOXB2 in open-access papers:
HOXB2 is named in the same sentence as 50 diseases in open-access papers, as found by Europe PMC text mining. Sharing a sentence is not in itself a finding about the gene and the disease. The quoted sentences say what the papers report.
breast carcinoma (11 papers, 2011 to 2024). "Survival analyses using Kaplan-Meier and MTCI databases revealed that lower HOXB2 expression was significantly associated with poor overall survival (OS) in patients with breast cancer." (PMID 38322121, 2024). "Meanwhile, low expression of HOXB2 was associated with poor OS in both patients with ER+ or PR+ breast cancer." (PMID 38322121, 2024). "Moreover, HOXB2 downregulation was associated with the poor OS not only in patients with breast cancer but also in patients with other solid tumors." (PMID 38322121, 2024). "Similarly, low HOXB2 expression was significantly associated with poor OS in patients with Grade I breast cancer." (PMID 38322121, 2024). "Furthermore, we showed that HOXB2 is associated with a network of downstream molecules responsible for ECM formation in breast cancer cells." (PMID 38322121, 2024). "Moreover, poor OS in patients with breast cancer was significantly associated with the concurrent downregulation of HOXB2, MATN3, and ECM2." (PMID 38322121, 2024). "HOXB2 is a downstream target of retinoic acid, a well-known differentiation inducer required to maintain the homeostasis of mammary gland morphogenesis, and once activated, HOXB2 encodes a transcription factor that negatively regulates growth in breast cancer cells." (PMID 25962646, 2015). "The HOXB-AS1 transcripts were significantly downregulated in patients with basal-like breast cancer with markedly lower expression of HOXB2 compared with other subtypes." (PMID 38322121, 2024). "Taken together, these results reveal that HOXB-AS1 is a positive upstream regulator of HOXB2 in breast cancer cell lines." (PMID 38322121, 2024). "Collectively, it strongly suggests that the aggressive phenotype of breast cancer cells is developed through the HOXB-AS1/HOXB2 transcriptional axis." (PMID 38322121, 2024). "To gain further insight into HOXB2 expression in breast cancer, we analyzed a microarray of gene expression from a publicly available TCGA dataset." (PMID 38322121, 2024). "Here, using a combination of in silico analyses of large-scale patient datasets, in vitro RNAi phenotyping, and in vivo validation studies, we investigated the role of HOXB2 in different molecular subtypes of human breast cancer (BC)." (PMID 38322121, 2024). "The expression levels of HOXB2 were similar between normal-like, luminal A, B, and HER2-enriched breast cancers; however, HOXB2 expression was significantly lower in basal-like breast cancer." (PMID 38322121, 2024). "The proportion of cases with HOXB2 alteration was significantly augmented in basal-like breast cancer compared to that in other subtypes." (PMID 38322121, 2024). "We found that breast cancers with metastasis to regional lymph nodes, the brain and the central nervous system (CNS), and the liver have low levels of HOXB2." (PMID 38322121, 2024). "Together, these results suggest that HOXB2 functions as an important component in the regulation of EMT in breast cancer cells." (PMID 38322121, 2024). "Further, as a result of grading analysis for HOXB2 in breast cancer using Oncomine, HOXB2 expression was found to be significantly lower in grade 3 tumors in 7 out of 14 existing microarray studies." (PMID 38322121, 2024). "Both MATN3 and ECM2 expressions were positively correlated with HOXB2 expression in the human breast cancer tissues." (PMID 38322121, 2024). "Analysis of an independent set of 207 ER- breast cancers from TCGA similarly confirmed hypermethylation at cg20401567 and reduced HOXB2 expression in tumors from Black versus White women (Rho=-0.75, FDR<0.001)." (PMID 37293596, 2023). "For paclitaxel we found that three genes were reported to be associated with ovarian cancer (HOXB2, MYC, and TFPI2; p=0.024) and two genes were strongly associated with tumorigenesis of breast cancer (DUSP2 and ITGA3; p<0.001)." (PMID 29416679, 2018).
breast carcinoma (continued). "On the other hand, suppression of HOXB2 increased tumor growth in mice xenograft models of breast cancer cell lines, and overexpression of HOXB2 induced apoptotic cell death in vitro in acute myeloid leukemia (AML)." (PMID 28465481, 2017). "By contrast, only 31.26% of the promoters of coding genes were aberrantly methylated in breast cancer, some of which were in known disease-related genes, such as HOXB2, FGF4 and TTK." (PMID 25739977, 2015). "Therefore, we utilized the Metastatic Breast Cancer Project data to determine the degree of metastasis depending on HOXB2 expression." (PMID 38322121, 2024). "In addition, this research not only confirmed that overexpression of HOXB2 was associated with better prognostic results through KM plot analysis, but also verified that HOXB2 was significantly underexpressed in higher grade breast cancer." (PMID 38322121, 2024). "This is because HOXB2 was found as a regulator of tumor growth in breast cancer." (PMID 23630576, 2013). "Moreover, our findings support a novel regulatory site for HOXB2 activity, which could be a potential therapeutic target in breast cancer treatment." (PMID 37293596, 2023). "Further, we identified the positive correlation between HOXB2 and HOXB-AS1 in breast cancer patients as well as cell lines using data retrieved from TANRIC and CCLE." (PMID 38322121, 2024). "Accordingly, we explored the relationship between the expression of HOXB2 and SMYD3 in breast cancer cell lines using data retrieved from CCLE dataset, and found a positive correlation." (PMID 38322121, 2024). "To further confirm the therapeutic efficacy of HOXB2/MATN3 or HOXB2/ECM2 transcriptional axis, we performed IHC for HOXB2, MATN3, and ECM2 in-house with 100 human tissue samples of patients with breast cancer." (PMID 38322121, 2024). "As HOXB2, MATN3, and ECM2 expressions positively correlated in breast cancer cells, we re-analyzed data from patient samples in publicly available clinical datasets of GSE65194 and GSE58812." (PMID 38322121, 2024). "Therefore, we further investigated the expression of HOXB2 and HOXB3 and their correlation with the clinical characteristics of patients with breast cancer." (PMID 38322121, 2024). "Nonetheless, a statistically significant relationship between HOXB2 and lymph node metastasis in patients with breast cancer could not be discerned from our in-house analysis." (PMID 38322121, 2024). "There was indeed a positive correlation between HOXB2 and both ESR1 and PGR, allowing the conclusion to be drawn that low expression of HOXB2 could lead to the transition of ER+ and/or PR+ breast cancers to express less hormone receptors, and display more aggressive phenotypes like TNBC." (PMID 38322121, 2024).
pancreatic cancer (10 papers, 2013 to 2024). "Overexpression of HOXB2 was shown to be associated with cancer progression in cervical cancer, pancreatic cancer, and lung adenocarcinoma." (PMID 28465481, 2017). "Finally, we examined two genes that were differentially enriched for H3K4Me3 only in WT mice, Hoxb2 and Axl, and linked to pancreatic cancer." (PMID 24465395, 2014). "HOXB2 was upregulated in pancreatic cancer as a part of the retinoic acid (RA) signaling pathway, which is generally regarded to be a potential anti-tumor agent." (PMID 25521548, 2014). "HOXB2 serves as a tumor promotor in bladder cancer, colorectal cancer, and pancreatic cancer." (PMID 34903206, 2021). "The overexpression of miRNA-10a has been observed to down-regulate the transcriptional suppressors and metastatic factors (homeobox transcription factors)—HOX (HOXB1, HOXB2, HOXA1) in various pancreatic cancer cell lines including, PANC-1, CAPAN-1, SUIT-2, KP-2 and MIA PaCa-2." (PMID 39200178, 2024). "It has previously been reported that some HOX genes are overexpressed in pancreatic tumors and they include HOXA10, HOXB7 and HOXB2, and transfection of Panc1 cells with siHOTTIP slightly decreased expression of HOXB7 but significantly decreased HOXA10 (>80%) and HOXB2 (>60%)." (PMID 25912306, 2015). "In pancreatic cancer cells, HOTTIP regulates HOXA10, HOXB2, HOXA11, HOXA9 and HOXA1, but not HOXA13." (PMID 30819158, 2019). "However, another study in pancreatic cancer cells demonstrated that HOTTIP did not modulate HOXA13 expression, but did regulate the expression of other HOX genes such as HOXA1, HOXA9, HOXA10, HOXA11 and HOXB2." (PMID 28938659, 2017).
bladder cancer (7 papers, 2010 to 2023). "We identified and confirmed that increased promoter methylation of HOXB2 is significantly and independently associated with invasive bladder cancer and methylation of HOXB2, KRT13 and FRZB together significantly predict high-grade non-invasive disease." (PMID 20808801, 2010). "In luminal infiltrated and luminal papillary subtypes of bladder cancer, HOXB2 mRNA expression was significantly upregulated." (PMID 37627900, 2023). "The knockdown of HOXB2 reduced the cell proliferation, adhesion, and invasion of bladder cancer in vitro." (PMID 37627900, 2023). "In non-invasive bladder cancers, a significantly greater extent of HOXB2, FRZB, and KRT13 methylation was detected in grade 3 tumors as compared to grade 1 and 2 tumors." (PMID 37627900, 2023). "Methylation of HOXB2, FRZB and KRT13 is independently associated with high grade disease in non-invasive bladder cancer." (PMID 20808801, 2010). "The methylation of HOXB2, FRZB, and KRT13 was greater in invasive bladder cancers as compared to non-invasive bladder cancers." (PMID 37627900, 2023). "Pyrosequencing was performed to determine the methylation status of HOXB2, FRZB, and KRT13 in bladder cancer cell lines HTB-9 and UM-UC3." (PMID 20808801, 2010). "HOXB2, FRZB, and KRT13 methylation status may be potential prognostic biomarkers to predict the likelihood of getting high grade non-invasive bladder cancer, that can subsequently be used to predict tumor recurrence or progression to muscle-invasion." (PMID 37627900, 2023).
glioblastoma (7 papers, 2020 to 2024). The most malignant astrocytic tumor (WHO grade IV). "Studies have shown that inhibition of miR-885-3p expression can antagonize HOXB-AS1 knockdown and further affect the expression of HOXB2 in human glioblastoma tissues and cells." (PMID 39280958, 2022). "HOXB-AS1/miR-885-3p/HOXB2 axis boosts the bio-behaviors of glioblastoma." (PMID 34872582, 2021). "Moreover, lncRNA HOXB‐AS1 promoted proliferation, migration and invasion of glioblastoma cells via miR‐885‐3p/HOXB2 axis." (PMID 32633082, 2020). "The proliferation, migration, and invasion of glioblastoma cells are regulated by HOXB-AS1, which modulates the miR-885-3p/HOXB2 axis." (PMID 39280958, 2022). "For instance, silencing of HOXB-AS1, HOXB2, or HOXB3 can lead to inhibition of cell proliferation and apoptosis stimulation of glioblastoma." (PMID 36045719, 2022).
glioma (5 papers, 2020 to 2024). A benign or malignant brain and spinal cord tumor that arises from glial cells (astrocytes, oligodendrocytes, ependymal cells). "In gliomas and osteosarcomas, it was observed that the downregulation of miR-1200, led to the up-regulation of the HOXB2 gene, which increased proliferation and invasion capacity of the tumor cells." (PMID 34315420, 2021). "miR-1200 was also reported to be sponged by long noncoding RNA (lncRNA) RGMB-AS1 and directly target HOXB2, suppressing proliferation, migration, and invasion in glioma cells." (PMID 32855967, 2020). "It has also been reported that lncRNA RGMB‐AS1 promoted glioma growth and invasion through miR‐1200/HOXB2 axis." (PMID 32633082, 2020). "Besides POLD4, HOXB2 was also demonstrated to be a direct target of miR-1200 and mediated the tumor-suppressing role in human osteosarcoma and glioma cells." (PMID 32855967, 2020).
osteosarcoma (5 papers, 2020 to 2024). A usually aggressive malignant bone-forming mesenchymal neoplasm, predominantly affecting adolescents and young adults. "The enhanced expression level of miR-1200 by circ-0001785 knockdown attenuated proliferative ability and induced the apoptosis of osteosarcoma cells; HOXB2 was a direct target of miR-1200." (PMID 32855967, 2020). "Consistent with our results, upregulation and carcinogenesis of HOXB2 have also been identified in osteosarcoma and ovarian cancer." (PMID 32633082, 2020).
ovarian carcinoma (5 papers, 2012 to 2024). A malignant neoplasm originating from the surface ovarian epithelium. "Many studies have found that HOXB cluster members are involved in the tumorigenesis or progression of ovarian cancer, including HOXB2, HOXB3, HOXB4, HOXB7, and HOXB8." (PMID 33815481, 2021). "For example, Module 37 includes four HOX family genes (HOXB2, HOXB4, HOXB6 and HOXB7) that all have been extensively reported to be related with ovarian cancer." (PMID 22863767, 2012).
endometrial cancer (4 papers, 2013 to 2022). Primary or metastatic malignant neoplasm involving the endometrium (mucous membrane that lines the endometrial cavity). "In our study, we found that reduced HOXB2 expression in whole blood was associated with endometrial cancer risk variation, compatible with reports that HOXB2 has a tumor-suppressor function." (PMID 31561579, 2019).
endometrial tumors (3 papers, 2013 to 2020). "Three of these associations were observed in whole blood (SNX11, HOXB2 and SRP14) and one in endometrial tumors (BCL11A)." (PMID 31561579, 2019). "Interestingly, we found HOXB2 was hypermethylated in endometrial normal tissues compared with endometrial tumors." (PMID 23630576, 2013).
lung carcinoma (3 papers, 2013 to 2024). "The same trend of worse prognosis was observed in patients with lung cancer, renal clear cell carcinoma, or hepatocellular carcinoma exhibiting low HOXB2 and/or low HOXB2/MATN3/ECM2 expression." (PMID 38322121, 2024). "HOXB2 also promotes the invasion of lung cancer cells by regulating metastasis-related genes." (PMID 25521548, 2014). "Moreover, HOXB2, HOXB4 and HOXB7 together showed the key function in lung cancers." (PMID 23630576, 2013).
breast tumors (2 papers, 2013 to 2023). "Reduced expression of HOXB2 in breast tumors from Black versus White women represents a novel molecular feature which may be linked to racial differences in breast tumor biology and outcomes." (PMID 37293596, 2023).
endometriosis (2 papers, 2021 to 2022). The growth of functional endometrial tissue in anatomic sites outside the uterine body. "As a downstream target gene of type I IFN, the upregulated HOXB2 expression is a putative implication of the altered IFN signaling in the endometrium of patients with endometriosis after surgery." (PMID 36171908, 2022). "Altered expressions of HOXB2, B3, B4, B7, and B9, which we observed in the endometriosis samples, correlated with previous reports for these genes in endometriosis and in progression and development of many cancers." (PMID 34470627, 2021). "Differential expressions of HOXB2, B3 and B4, and the HOXD2 and D3 genes, which we detected in the current study, agreed with previous reports on endometriosis." (PMID 34470627, 2021).
lung adenocarcinoma (2 papers, 2017 to 2021). A carcinoma that arises from the lung and is characterized by the presence of malignant glandular epithelial cells. "Up‐regulation of HOXB2 was found to be an adverse prognostic indicator for stage I lung adenocarcinoma, promoting invasion by transcriptional regulation of metastasis‐related genes." (PMID 34184409, 2021).
sarcopenia (2 papers, 2024 to 2025). Progressive decline in muscle mass due to aging which results in decreased functional capacity of muscles. "Among them, MYH8, HOXB2, C1QA, CDKN1A, and SLC38A1 are associated with sarcopenia, and in this study, LGR5, SERPINA5, and TPPP3 genes were found to be associated with Sarcopenia for the first time." (PMID 38229116, 2024). "In patients with sarcopenia, the expression of TPPP3, C1QA, LGR5, MYH8, and CDKN1A genes are upregulated, and the expression of SLC38A1, SERPINA5, and HOXB2 genes are downregulated." (PMID 38229116, 2024).
adenomyosis (1 paper, 2022). The growth of endometrial tissue inside the muscular wall of the uterine corpus. "HOXB2, a relatively less studied member of the homeobox genes in the endometrium is upregulated in type I IFN response, and one study pointed out that the response to IFN signaling is dysregulated in the eutopic endometrium of patients with adenomyosis during the secretory phase." (PMID 36171908, 2022).
Arboleda-Tham Syndrome (1 paper, 2022). "The first and second DMRs overlap regions of HOXB2, HOXB3 and HOXB4 and is hypomethylated in Arboleda-Tham Syndrome patients relative to controls." (PMID 36064314, 2022).
autosomal dominant polycystic kidney disease (1 paper, 2021). Autosomal dominant form of polycystic kidney disease. "Expression of the lncRNA Hoxb3os (homeobox B3 and homeobox B2, opposite strand) is significantly decreased in the renal tissues of patients with autosomal dominant polycystic kidney disease (ADPKD) and in a mouse model of ADPKD." (PMID 33681192, 2021).